GFER (growth factor, augmenter of liver regeneration)
Description:
[Isoform 1]: FAD-dependent sulfhydryl oxidase that regenerates the redox-active disulfide bonds in CHCHD4/MIA40, a chaperone essential for disulfide bond formation and protein folding in the mitochondrial intermembrane space. The reduced form of CHCHD4/MIA40 forms a transient intermolecular disulfide bridge with GFER/ERV1, resulting in regeneration of the essential disulfide bonds in CHCHD4/MIA40, while GFER/ERV1 becomes re-oxidized by donating electrons to cytochrome c or molecular oxygen. [Isoform 2]: May act as an autocrine hepatotrophic growth factor promoting liver regeneration.
Synonyms: hERV1; ALR; HPO; HSS; ERV1; HPO1; HPO2; MMCHD; MPMCD
Tractability: Small molecule: a structure with a bound ligand is known; it belongs to a druggable protein family. Antibody: UniProt places it where antibodies can reach, with medium confidence; its Gene Ontology location is reachable by antibodies, with medium confidence. PROTAC: ubiquitination databases record sites on it; its protein half-life has been measured; a small molecule that binds it is known.
Target class: Enzyme
Gene: Protein-coding gene on chromosome 16 (1,984,193 to 1,987,749, forward strand). Ensembl gene ENSG00000127554.
Subcellular location: Mitochondrion intermembrane space (Isoform 1); Mitochondrion; Cytoplasm (Isoform 2); Secreted
Subcellular location (Human Protein Atlas): Cytosol; Mitochondria; Predicted to be secreted
Pathways (Reactome):
Protein localization: Mitochondrial protein import
Gene Ontology:
Molecular function: flavin adenine dinucleotide binding; flavin-dependent sulfhydryl oxidase activity; protein binding; protein-disulfide reductase activity; thiol oxidase activity
Biological process: mitochondrial disulfide relay system; liver development
Cellular component: cytosol; mitochondrion; cytoplasm; extracellular region; mitochondrial intermembrane space
Genetic constraint (gnomAD): Loss-of-function variants: 24 observed, 17 expected, observed/expected ratio (o/e) 1.41, 90% interval 1.02 to 1.87. The upper end of that interval is the gene's LOEUF score, 1.87, which puts it in group 6 of 6, group 1 being the genes least tolerant of losing a copy. Missense variants: 316 observed, 263.71 expected, observed/expected ratio (o/e) 1.2, 90% interval 1.09 to 1.32. Synonymous variants: 138 observed, 111.99 expected, observed/expected ratio (o/e) 1.23, 90% interval 1.07 to 1.42.
Gene-disease validity (ClinGen):
ClinGen rates the evidence that GFER causes each of these diseases.
mitochondrial disease (autosomal recessive): Definitive.
Homologues: Orthologues: chimpanzee GFER (99% identical), macaque GFER (95% identical), pig GFER (89% identical), dog GFER (87% identical), guinea pig GFER (81% identical), mouse Gfer (75% identical), rat Gfer (74% identical), zebrafish gfer (47% identical), Drosophila melanogaster Alr (38% identical), Caenorhabditis elegans F56C11.3 (33% identical).
Diseases named in the same sentence as GFER in open-access papers:
GFER is named in the same sentence as 14 diseases in open-access papers, as found by Europe PMC text mining. Sharing a sentence is not in itself a finding about the gene and the disease. The quoted sentences say what the papers report.
colitis (1 paper, 2025). Inflammation of the colon. "In summary, by integrating scRNA‐seq and bulk transcriptomic data, we identified the protective role of the ferroptosis‐related mitochondrial gene GFER in enterocyte cells during colitis." (PMID 41098076, 2025). "Similarly, in a DSS‐induced colitis mouse model, GFER expression was markedly reduced in the DSS group compared to the WT group." (PMID 41098076, 2025).
hepatocellular carcinoma (1 paper, 2021). A malignant tumor that arises from hepatocytes. "For example, ERV1/ALR/GFER has been linked to hepatocellular carcinoma (HCC), with one study showing that a liver-specific knockout in mice caused accelerated development of HCC." (PMID 33599699, 2021).
GFER also shares sentences with these, for which no sentence is quoted: cancer (1 paper); colorectal adenocarcinoma (1); colorectal adenoma (1); developmental delay (1); intrahepatic cholangiocarcinoma (1); Li-Fraumeni syndrome (1); myopathy (1); pancreatic disease (1); tumor (1); type 1 diabetes (1); type 2 diabetes (1); viral infection (1).